EGFR (epidermal growth factor receptor)
Diseases named in the same sentence as EGFR in open-access papers (continued):
Sharing a sentence is not in itself a finding about the gene and the disease.
tumor (continued). "Furthermore, radioconjugate tumor accumulation was confirmed to be EGFR-specific, as PET imaging of MCF-7 (EGFR+) showed much lower accumulation of the radioconjugate than tumors with higher receptor expression." (PMID 30213849, 2019). "Consequently, neutralization of EGFR signaling by blocking EGFR binding sites on the extracellular domain represents a plausible strategy to prevent EGFR-expressing tumor growth." (PMID 31546749, 2019). "Third, tumor microenvironmental changes, a rather small window, may be most beneficial for combination EGFR blockade with immune-mediated anticancer approaches, which were found to only be temporary and disappeared as treatment continued." (PMID 31526368, 2019). "The majority of EGFR genotyping is assessed through conventional tumor biopsy." (PMID 31582907, 2019). "Furthermore, tumor targeting by the radioconjugate correlated with EGFR expression measured ex vivo by Western blot analysis and immunohistochemical staining." (PMID 30213849, 2019). "Furthermore, we investigated the effect of various nanoparticles on the expressions of EGFR and Notch in tumor tissues." (PMID 30957572, 2019). "The latest evidences strongly suggest that complex molecular alterations coupled with changes in the tumor microenvironment may substantially contribute to the clinical efficacy of EGFR antagonists, even in CRC that are both KRAS and NRAS wild type." (PMID 31370270, 2019). "Previous studies showed that the higher expression of EGFR indicated higher tumor heterogeneity." (PMID 31174617, 2019). "Recently, clinical implications of primary tumor side started to be analyzed in the metastatic setting, providing evidence that right-sided tumors have a worse prognosis and are less sensitive to anti-EGFR therapy." (PMID 30691222, 2019). "Indeed, in patients with EGFR mutations, the effect of postoperative EGFR-TKI treatment seemed to overwhelm the influence of main tumor resection on overall survival." (PMID 29435191, 2018). "We demonstrate here the differential survival outcomes of main tumor resection in patients with and without EGFR mutation." (PMID 29435191, 2018). "EGFR TKIs have been shown to be effective against tumours exhibiting EGFR activating mutations, but lack efficacy in tumours without these mutations." (PMID 30409180, 2018). "The oncogenic EGFR was recently shown to aberrantly bind to Beclin-1, which might contribute to tumor progression and chemoresistance." (PMID 30237564, 2018). "Given that AZD7451 inhibits TrkB activation and tumor cell migration, as well as the observed crosstalk between EGFR and TrkB in other malignancies, we then combined this agent with erlotinib to determine the effect on multiple SCC and adenocarcinoma cell lines." (PMID 29581842, 2018). "Supporting these data, our ex vivo slice cultures demonstrated increased tumor cell migration in EGFR-amplified tumors, and blockade of EGFR signaling with the small molecule inhibitor, gefitinib, induced a statistically significant reduction in migratory behavior within the same sample set11." (PMID 30573757, 2018). "The problem is that these patients are good candidates for anti-EGFR antibody treatment because they have no KRAS mutations in tumor tissues before treatment." (PMID 29849949, 2018). "Collectively, these data indicate that CCDC115 expression could be impeding tumor growth in our current study via several mechanisms, including disruption of the EGFR or FGF2/MAPK pathways." (PMID 29890952, 2018).
tumor (continued). "Thus, EGFR modulation had opposing effects on tumor burden when pharmacological agents were administered after mucosal healing compared to active injury." (PMID 29904166, 2018). "WES showed that the tumor from patient CTC15063EGFR L858R, T790M, the osimertinib-sensitive CTC15063EGFR L858R, T790M xenograft tumors, and the osimertinib-resistant osimertinib-3 tumor had the EGFR mutations, L858R and T790M." (PMID 29764505, 2018). "Other groups also reported that sortilin promotes exosome release and forms a complex with two tyrosine receptors, tropomyosin-related kinase B (TrkB) and epidermal growth factor receptor, which play an important role in the control of the cancer cell microenvironment and tumor angiogenesis." (PMID 29382723, 2018). "In line with these binding data, the monovalent α-EGFR TM stimulates UniCAR T cells only to attack tumor cells expressing high levels of EGFR, while the bivalent α-EGFR-EGFR TM engages UniCAR T cells even for an efficient lysis of cancer cells expressing low levels of EGFR." (PMID 29876011, 2018). "Interestingly, tumour epithelium was associated with HER2 deregulation and aberrant expressions of EGFR and HGFR followed by upregulation of inflammatory cytokines in stroma regions." (PMID 29455663, 2018). "The presence of EGFR and KRAS mutations is also mutually exclusive in the same tumor." (PMID 29371589, 2018). "The rapid emergence of resistance to EGFR TKIs27,28 seems counter intuitive in the context of low-mutation burden, and the impact of intra-tumor heterogeneity on the extent of tumor shrinkage and eventual emergence of drug resistance is not well established." (PMID 29335443, 2018). "Upregulation or oncogenic activation of EGFR can lead to uncontrolled growth and tumor progression." (PMID 30408128, 2018). "Similar to EGFR, the KRAS status may also be discordant between primary and metastatic tissues and a KRAS mutation in a small subset of tumor cells may confer resistance to EGFR tyrosine kinase inhibitors (TKIs) therapy." (PMID 29868480, 2018). "In contrast, in tumor-associated perivascular areas without amplified EGFR strong SLUG and TWIST expression was detected." (PMID 29844871, 2018). "Tumor hypoxia is a well-established cause of treatment resistance, adversely affects the prognosis of HNSCC, and moderates the expression and activation of EGFR." (PMID 30083516, 2018). "Moreover, high frequency of recurrence was noted in patients with tumor showing intermediate and strong EGFR expression." (PMID 29879970, 2018). "EGFR inhibition with the TKI gefitinib led to decreased PD-L1 expression in NSCLC tumor cell line models and EGFR-induced PD-L1 expression was shown to be dependent upon ERK1/2 signaling down-stream of EGFR as treatment with the ERK1/2 inhibitor SCH772984 also led to diminished PD-L1 expression." (PMID 30420856, 2018). "The expression of EGFR seems to be dependent on the site of tumor development." (PMID 29850390, 2018). "The tumor harbored neither the epidermal growth factor receptor (EGFR) gene mutation nor the anaplastic lymphoma kinase (ALK) gene rearrangement." (PMID 29378571, 2018). "However, the cross talk between TGF‐β and EGFR signaling in promoting cancer progression has been observed in several tumor types." (PMID 29215776, 2018). "When we tested the EGFR activation in clinical samples by measuring the phosphorylation of tyrosine-1173 it became clear that in contrast to the expression levels, EGFR phosphorylation was even significantly lower in tumor versus normal adjacent tissue." (PMID 29989001, 2018). "As expected, EGFR TKI treatment dramatically reduced the tumor size when compared to control mice." (PMID 30097569, 2018).
tumor (continued). "Inhibitors of EGFR signaling, such as Erlotinib and Gefinitib could significantly repress tumor growth, but the drug resistance is still a problem during treatment." (PMID 29691367, 2018). "In fact, EGFR-IR700 was shown to selectively destroy EGFR-positive A431 cells in the presence of EGFR-negative cells in a mixed tumor model, while adenoviral infection with Tra-IR700 destroyed only HER2-expressing cancer cells with minimal cytotoxicity to non-infected cells." (PMID 30140380, 2018). "Because CSCs contribute to drug resistance and tumor recurrence, the Compound Screening Library (MedChemExpress, NJ, USA) targeting stem cells was used for identifying the potential therapeutics against EGFR-positive CRCs." (PMID 30068339, 2018). "7A7 was unable to impact tumour growth in an EGFR-expressing HPV38 transplantable SCC tumour model." (PMID 29552307, 2018). "Comparison of tumor and cfDNA EGFR T790M and osimertinib treatment response." (PMID 30444875, 2018). "The Half DVD-Ig also showed binding to the EGFR expressing tumor cell line A431 but the binding to CD3 expressed on Jurkat cells was greatly reduced compared to DVD-Ig, which is most likely due to a significant loss in binding associated with a monovalent anti-CD3." (PMID 28585177, 2018). "Although the [68Ga]-Pentixafor-PET/CT revealed the probable primary tumor, the bioinformatics analyses of gene expression data could not support our assumption that CXCR4 expression and the mutation status of EGFR are linked." (PMID 29721166, 2018). "For example, the correlation of CDH1 mutations to the activation of WNT, EGFR, and AKT pathways as well as the inactivation of tumor suppressors, such as EPHB3 and IGSF8, provides several hypotheses to test." (PMID 29520031, 2018). "Masking phosphatidylserine (PS), present in the membrane surface of EVs, by Diannexin and blocking its receptor TIM4 inhibits epidermal growth factor receptor (EGFR) transfer from tumor EVs to endothelial cells resulting in reduced tumor growth and microvascular density in vivo." (PMID 30369925, 2018). "False-positive results were defined as EGFR mutation-positive in plasma and mutation-negative in tumor samples and were observed in 4 patients (rate of 2.8%)." (PMID 29623586, 2018). "Moreover, our results show a different level of expression of EGFR at the tumor EV RNA level between patients and healthy donors, similar to previous reports using protein analysis." (PMID 29330365, 2018). "One possible hypothesis is that tumours of patients in this group may retain partial sensitivity to EGFR‐TKI treatment, and may respond clinically if EGFR‐TKI is used in combination with treatments targeting additional resistance pathway." (PMID 29848757, 2018). "Patients whose tumours harboured an EGFR mutation were the only subgroup not to benefit from immunotherapy compared with docetaxel in these trials." (PMID 29904031, 2018). "Furthermore, systemic delivery of the nanoparticles carrying the siRNAs to suppress the expression of ER/BCL-2 and ER/ERBB2/EGFR groups of proteins resulted in a notable and sustainable decrease in tumor growth in a 4T1-induced syngeneic mouse model." (PMID 29932151, 2018). "In contrast, EGFR mutations in patients with carcinoembryonic antigen levels ≥ 2.12 ng/mL were associated with age (P = 0.002), nonsmokers (P = 0.038), tumour size (P = 0.010), histology (P < 0.001), and stage (P < 0.001)." (PMID 29849818, 2018). "By contrast, in four cases, the EGFR mutation status was positive in the plasma sample and negative in the tumor sample." (PMID 29623586, 2018). "Furthermore, we used slice culture of the patient’s GBM explant to evaluate the tumour’s sensitivity to various EGFR-targeting drugs." (PMID 30305059, 2018). "While the monovalent α-EGFR TM could only mediate the killing of tumor cells expressing high levels of EGFR, the bivalent α-EGFR-EGFR TM could redirect UniCAR T cells to tumor cells expressing low levels of EGFR." (PMID 29876011, 2018).
tumor (continued). "We hypothesize, that the simultaneous inhibition of EGFR and uPAR/α5β1 mediated signals, which is induced by the combination treatment on tumor cells, leads to a quite effective form of immunogenic cell death." (PMID 29844873, 2018). "Subsequent studies indicated that miR-542-5p could also play a role as a tumor suppressor in various cancers by directly binding to EGFR." (PMID 30467286, 2018). "The results in toto suggest that MR30 is the first prototype of agents that may be used against tumours addicted to EGFR and to sensitize resistant tumours co-expressing EGFR and MGMT to TMZ." (PMID 30416678, 2018). "Taken together, the association of blood S100A9+ MDSCs with treatment response to EGFR-TKIs might be through an interaction with tumor cells by themselves and their derived macrophages." (PMID 29484139, 2018). "In addition to NBs, human glioblastoma multiforme tumours also express TrkAIII, including an EGFR and EGFRvIII negative subpopulation, suggesting that TrkAIII represents a potential oncogenic alternative to EGFR and EGFRvIII oncogenes in this tumour type." (PMID 29914559, 2018). "Thus, our findings highlight the importance of the OGN-mediated of EGFR signaling in tumor biology, revealing a novel mechanism regulating CRC growth and progression." (PMID 29499765, 2018). "Since we found, using cell models, that IGFBP-3 downregulation attenuated the synergism between the EGFR and SphK inhibitors, we proposed that tumor IGFBP-3 levels might act as a biomarker for the efficacy of the combination therapy." (PMID 29623068, 2018). "Main tumor resection was not a prognostic factor in patients with EGFR mutations and EGFR-TKI treatment history (P = 0.857)." (PMID 29435191, 2018). "In contrast, tumor cell binding of the monovalent α-EGFR TM could only be verified for cell lines with high or intermediate EGFR expression namely A431 cells and FaDu cells." (PMID 29876011, 2018). "Moreover our study shows that oxaliplatin and anti-EGFR-based chemotherapy are effective therapy to promote CD8 recruitment in WT RAS tumor." (PMID 30454021, 2018). "For example, recent reports have indicated that EGFR T790M may be identified in cfDNA but missing in tumor biopsy samples." (PMID 30444875, 2018). "We next sought to determine if biasing EGFR signaling could change the EGF response of primary tumor cells from proliferative to apoptotic." (PMID 30250119, 2018). "EGFR mutations were confirmed to be truncal events (mutations present in all sectors of a tumor) in every case regardless of the mutation type (L858R, exon 19 deletion or exon 20 insertion), underscoring its role as an early tumor initiating driver event." (PMID 29335443, 2018). "Besides the potent tumor-specific costimulation, the 1D8N/CEGa1 trimerbody exhibit improved serum stability as well as efficient and rapid localization to EGFR-positive tumors." (PMID 30442944, 2018). "Consequently, the co-administration of anti-EGFR mAbs, checkpoint inhibitors and autophagy inhibitor can attenuate tumor growth." (PMID 30427914, 2018). "In some tumor samples, total EGFR was observed to be increased after anti-ErbB3 antibody treatment." (PMID 29305574, 2018). "However, the same was true for HPV38 tumours, which we were able to confirm express EGFR by multiple methods." (PMID 29552307, 2018). "Guan's group identified tumor size as a predictor for EGFR mutation on multivariate analysis, which is not consistent with our study." (PMID 29164298, 2018). "Constitutive autocrine activation might lead to clonal expansion and tumor formation, and autocrine activation of various RTKs has been well characterized in diverse cancers, including TGFα-EGFR, HGF-MET, and SCF-KIT autocrine loops." (PMID 29455648, 2018).
tumor (continued). "A great body of studies have disclosed that the tumorigenesis and progression of HCC are implicated with the mutation and abnormal expression and of genes, involving epidermal growth factor receptor (EGFR), cyclin D1 (CCND1), FoxQ1, c-myc, as well as mutations of some tumor-suppressor genes." (PMID 29977454, 2018). "Only the primary tumor and its derived gliomaspheres exhibited EGFR and MDM4 amplification." (PMID 29416795, 2018). "What is more, in different types of cancer, overexpression and mutation of the epidermal growth factor receptor (EGFR) have been observed; thus, finding inhibitors of EGFR kinases among (thio)ureido-quinazoline derivatives is also a promising approach to tumor treatment." (PMID 30248936, 2018). "Among the novel top 80 candidate cancer genes, we mechanistically characterized the function of the top hit, the Tetraspanin family member Tsp29Fb, revealing that Tsp29Fb regulates EGFR signaling, epithelial architecture and restrains tumor growth and invasion." (PMID 30325918, 2018). "We hypothesized that the accumulation of NGcGM3 in the cell membrane, ensures optimal EGFR and uPAR/α5β1 integrin pathways signaling, promoting tumor growth and metastasis dissemination." (PMID 29844873, 2018). "While the internalization and fast EGFR turnover in tumor tissue leads to increased fluorescent signal due to dye accumulation inside tumor cells, variability in expression status may affect fluorescence accumulation and therefore fluorescent signal." (PMID 29623552, 2018). "Of note, a randomized phase II trial, the S1613 study, has been recently opened to explore the efficacy of trastuzumab and pertuzumab compared to cetuximab and irinotecan in pre-treated anti-EGFR naïve mCRC patients carrying a tumor with HER2/neu amplification." (PMID 34532592, 2018). "Moreover, the overexpression of EGFR has been verified to promote tumor growth and progression, including maturation, angiogenesis, invasion, metastasis, and inhibition of apoptosis." (PMID 30513793, 2018). "Growing in-vitro and in-vivo evidence suggests that HER2 might be overexpressed more frequently in patients with EGFR-dependent (all wild-type) tumours." (PMID 29254887, 2018). "However, binding of the dodecavalent LC/HC-scTRAIL to EGFR and TRAIL receptors on EGFR+ tumour cells was shown to be similar compared to hexavalent formats, suggesting a rather stronger reduction of bioactivity than observed upon competition with cetuximab." (PMID 29773864, 2018). "MUC1 drives tumor progression in multiple tumor types through activating important oncogenic proteins including EGFR, β‐catenin, NF‐κB, PKM2, and other pathways." (PMID 30024105, 2018). "Furthermore, we selected a low affinity EGFR antibody as the backbone for RN765C to achieve differential binding on normal cells versus tumor cells expressing medium to high levels of EGFR." (PMID 30323890, 2018). "Moreover, combining AZ304 and the anti-EGFR monoclonal antibody Cetuximab resulted in significantly improved anti-tumour activity in colorectal cancer cells both in vitro and in vivo, independently of BRAF mutation status." (PMID 29755114, 2018). "Given that (i) EGFR alterations are the most frequent genomic defects in GBM, and (ii) a number of targeted therapies are on the market, we performed short-term cultures of neurosurgical tumour resections with the EGFR-targeting drugs cetuximab, erlotinib and afatinib." (PMID 30305059, 2018). "miR-3140 suppresses other tumor promoting genes, such as EGFR and CDK2, via 3′UTR." (PMID 29540837, 2018). "On immunofluorescence staining, the surviving nab-paclitaxel-resistant tumour cells showed a significant increase in Snail and EGFR expression and docetaxel-resistant tumour cells showed a significant increase in Snail, consistent with a more aggressive phenotype." (PMID 29311580, 2018).